IL6 (interleukin 6)
Diseases named in the same sentence as IL6 in open-access papers (continued):
Sharing a sentence is not in itself a finding about the gene and the disease.
pancreatitis (continued). "Moreover, the levels of Th1 inflammatory mediators including IL-6, IL-1β, IFN-γ, and TNF-α decreased in pancreatic tissue after fucoidan intervention, indicating that fucoidan could relieve Th1 cells and Th1 cytokine-mediated pancreatitis locally." (PMID 38164477, 2024). "Indeed, we observed that induction of pancreatitis robustly increased plasma concentration of several inflammatory cytokines including IL1α (2.6-fold), IL1β (12.8-fold), VEGF (70.5-fold) TNFα (4.5-fold), and IL6 (585.2-fold) as well as stimulated p38 kinase activation in pancreatic tissue." (PMID 24480543, 2014). "In a caerulein-induced AP model characterized by mild, non-lethal pancreatitis without multiple organ dysfunction, DHA pretreatment led to decreased NF-κB activation, IL-6, lipid peroxide production, and inflammatory cell infiltration in the pancreas." (PMID 38785535, 2024). "The administration of 90 μg/kg G-CSF 1 hour before the induction of pancreatitis in rats increased the number of peritoneal-exudate neutrophils and circulating neutrophils without increasing the concentration of TNF-α, IL-6, and IL-1β." (PMID 25551560, 2014). "However IL-6 levels before and 12 hours afterERCP in both patients with ERCP-induced pancreatitis and without pancreatitiswere not observed differently from each other." (PMID 18670651, 2008). "Instead, we employed a NF-κB-mediated dermatitis, because we did not have a model of pancreatitis, and we wished to investigate whether GGT1-mediated NF-κB activation plays a role in the development of inflammatory diseases in vivo via the IL-6 amplifier activation." (PMID 38806529, 2024). "In the patients without post-ERCP pancreatitis, a positive correlationwas found between IL-4 and TNFα levels at 24 hours after ERCP (r = 0.397; P = .018),but there was a negative correlation between IL-4 and IL-6 levels at 12 hoursafter ERCP (r = 0.392; P = .018)." (PMID 18670651, 2008).
pulmonary hypertension (133 papers, 2007 to 2026). Increased pressure within the pulmonary circulation due to lung or heart disorder. "Preoperative echocardiographic pulmonary artery systolic pressure was found to be associated with the levels of IL-6 and IL-10 after surgery in pulmonary hypertension patients." (PMID 40020755, 2025). "HIV stimulates monocytes, macrophages, and lymphocytes to secrete proinflammatory cytokines associated with the development of idiopathic pulmonary hypertension: IL-1, IL-6, TNF, and platelet-derived growth factor." (PMID 41303627, 2025). "In conclusion, our study demonstrates that a lung specific transgenic mouse model that over-expresses IL6 is associated with cardiopulmonary fibrosis and pulmonary hypertension." (PMID 38650935, 2024). "In other tissues, IL-6 has been shown to be produced by EndoMT cells, and that it is associated with EndoMT processes in pulmonary arterial hypertension, cardiac valves, and fibrosis in hearts and kidneys." (PMID 37795485, 2023). "Transgenic overexpression of IL-6 in animal models promotes pulmonary hypertension; conversely, IL-6-deficient mice are protected from hypoxia-induced pulmonary hypertension." (PMID 34588193, 2022). "For example, in the absence of active ABR, hypoxia induces GTP-bound form of Rac, thus causing enhanced production of IL-6 during the pathogenesis of pulmonary hypertension." (PMID 31823748, 2019). "Administration of IL-6 is sufficient to cause pulmonary vascular remodeling in rodents and its over-expression spontaneously caused experimental pulmonary hypertension (PH)." (PMID 27835955, 2016). "In a recent study, the IL-6/IL-31-signaling axis was found to be critical for the pathogenesis of pulmonary arterial hypertension, with evidence of a strong association with M2-like macrophage infiltration." (PMID 27091114, 2016). "This study suggests that the p38 MAPK and the α-isoform plays a pathogenic role in both human disease and rodent models of pulmonary hypertension potentially mediated through IL-6." (PMID 26024891, 2015). "In the prevention study of the chronic hypoxic-associated pulmonary hypertension we found a reduction in IL-6 levels in the lungs of SB203580 drug-treated animals compared with vehicle-treated hypoxic controls." (PMID 26024891, 2015). "IL-6 is a known mitogen for vascular smooth muscle cells, and previous transgenic murine studies have implicated IL-6 in the etiology of pulmonary hypertension." (PMID 26024891, 2015). "We also noted that IL-6 and IL-13 levels were increased in patients with pulmonary hypertension, and that TNFα levels were associated with the presence of renal crisis." (PMID 19799786, 2009). "In addition, many studies show that in chronic lung disease with pulmonary hypertension, there is an association with increased levels of IL-6." (PMID 39727646, 2024). "ZC3H12A deficiency in mouse alveolar macrophages represented severe pulmonary arterial hypertension, while IL-6 and IL-1β may have served as potential targets for ZC3H12A in alveolar macrophages." (PMID 37504305, 2023). "In addition, mice with IL-6 deficiency exposed to hypoxia showed reductions in pulmonary hypertension, vascular remodeling, and macrophage recruitment in the lung." (PMID 34434114, 2021). "Furthermore, recombinant HERV-K dUTPase increased IL-6 in PA endothelial cells (PAECs) and caused pulmonary hypertension in rats." (PMID 34185707, 2021). "The purpose of this present study was to reveal the regulatory effects of trimethoxystilbene on the serum levels of nuclear factor kappa B, interleukin-6, and tumor necrosis factor-α in a rat model of pulmonary artery hypertension and to explore the possible underlying mechanisms." (PMID 31886168, 2019). "Although p38 MAPK has been implicated previously in cytokine biosynthesis and to have a role in MCT-induced pulmonary hypertension, this study is the first to show that the α-isoform is specifically implicated and inhibition can lower IL-6 levels and reverse disease." (PMID 26024891, 2015).
pulmonary hypertension (continued). "Previous studies have established that lesions due to pulmonary arterial hypertension could cause activation of macrophages which subsequently secretes several cytokines including IL-6 and TNF-α." (PMID 26391589, 2015). "In addition, elevated serum levels of IL-6 have been associated with dyspnea, skeletal muscle weakness, pulmonary arterial hypertension, and COPD exacerbations." (PMID 23626814, 2013). "Taken together, the IL-6 data are suggestive of a persistent pro-inflammatory state post-TB (seeing that the TB has clinically resolved), at least in population 1, which could predispose these patients to several post-TB sequelae, like pulmonary hypertension." (PMID 40407654, 2025). "IL-6 plays a pivotal role in pulmonary hypertension associated with COPD, and in vitro studies show that atorvastatin suppresses IL-6 production in endothelial cells." (PMID 41555409, 2026). "Elevated IL-6 transcription levels have been detected in the right ventricular tissue of patients with pulmonary arterial hypertension and decompensated right ventricular dysfunction." (PMID 40863398, 2025). "Right ventricular function is negatively affected in patients with pulmonary arterial hypertension, due to the activation of the inflammation/fibrosis axis; this axis contributes to elevated levels of IL-6 (Interleukin 6) in these patients." (PMID 40863398, 2025). "In this study of hypoxic pulmonary hypertension, epithelial derived IL‐18 can be a trigger of pulmonary inflammation and pulmonary hypertension via IL‐6 generation in infiltrating monocytes/macrophages and STAT3 signaling." (PMID 39034131, 2024). "It has been demonstrated that obeticholic acid reduces pulmonary IL-6 mRNA expression and attenuates right ventricular hypertrophy, pulmonary vascular remodeling, and pulmonary hypertension in a rat model of PAH with wild lily alkaloids." (PMID 39470277, 2024). "IL-6 at cut off point 1.45 ng/L significantly predict pulmonary hypertension in children (AUC = 0.685, 75% sensitivity, and 65% specificity with p = 0.002)." (PMID 38193997, 2024). "Experimental studies revealed a crosstalk between IL-6 and the bone morphogenetic protein BMP/SMAD pathway, and mutations of BMPR2 were associated with pulmonary hypertension and iron deficiency." (PMID 38999801, 2024). "IL-1, IL-6 and TNF-α protein levels were shown to be closely associated with PI3K/Akt signaling pathway activation in early stages of monocrotaline-induced pulmonary hypertension in rats." (PMID 36670454, 2023). "Direct determination of PH in COPD is traumatic, so it is of great clinical significance to detect hs-CRP, IL-6, IL-10, and ET-1 to monitor pulmonary hypertension." (PMID 35186226, 2022). "SAS-induced chronic intermittent hypoxia stimulates the secretion of inflammatory cytokines like IL-6, TNF-α, and CPR, and it causes pulmonary hypertension." (PMID 35871643, 2022). "This study shows that maternal and perinatal obesity cause bronchial and vascular smooth muscle cell proliferation through an IL-6-FoxO1 axis, and favor thereby the emergence of bronchial obstruction and pulmonary hypertension later in life." (PMID 35896539, 2022). "Clinically, an elevated central–peripheral temperature difference and pulmonary hypertension as well as increased IL-6 and CRP concentrations in blood samples were indicative of neonatal sepsis." (PMID 36233706, 2022). "For instance, astragalus polysaccharides decrease levels of the inflammatory cytokine TNF-α, IL-1β and IL-6 to resist pulmonary artery hypertension induced by MCT." (PMID 35033157, 2022). "During pulmonary hypertension, pulmonary vascular and surrounding tissues secrete a large amount of IL-6, promoted the proliferation of pulmonary vascular smooth muscle cells and endothelial cell s." (PMID 33971931, 2021). "We showed that recombinant HERV-K dUTPase can induce IL-6 production in PAECs as well as the activation of B cells and pulmonary hypertension in rats." (PMID 34185707, 2021).
pulmonary hypertension (continued). "Pulmonary hypertension was improved by IL-6 inhibition, although increased mast cell density persisted when IL-6 was diminished." (PMID 34566974, 2021). "IL-6 was found to accompany the development of hypoxia-induced pulmonary hypertension and is an important factor in the pathogenesis of PAH." (PMID 34442052, 2021). "Studies have shown that in the hypoxia-induced PH model, IL-6 mRNA and protein expression levels are increased, and pulmonary hypertension and right ventricular hypertrophy are improved in the IL-6 gene-knockout mous e." (PMID 33971931, 2021). "Inflammation can function as an essential role in development of pulmonary arterial hypertension, including IL-6." (PMID 34334083, 2021). "Earlier studies showed that, in general, patients with pulmonary hypertension demonstrated TNFα serum levels within the normal range, but had increased serum levels of IL-1 beta and IL-6 in severe primary pulmonary hypertension." (PMID 31024947, 2019). "Recently, relationships between increased circulating IL-6 levels and right ventricular (RV) function in pulmonary arterial hypertension patients have been analyzed." (PMID 31739518, 2019). "IL-6-transgenic mice are characterized by elevated plasma IL-6 levels as well as a number of outward phenotypes, including pulmonary hypertension." (PMID 29186034, 2017). "IL-6 is another inflammatory cytokine that has been shown to involve significantly in the pathogenesis of pulmonary artery hypertension and hypoxia-induced pulmonary hypertension." (PMID 27886226, 2016). "In IL6- and PH-Fib- (pulmonary hypertension adventitial fibroblast) stimulated macrophages, the blocking of STAT3 signalling gave rise to increased expression of STAT3-regulated genes associated with increased and prolonged STAT1 phosphorylation." (PMID 26512722, 2015). "Experimental evidence: Increased levels of IL-6 mRNA were measured in MCT rats that developed pulmonary hypertension and right ventricular hypertrophy (RVH)." (PMID 24739042, 2014). "It is the authors’ view that the best-investigated and most promising cytokine to date is IL-6, in particular for the development of hypoxia-induced pulmonary hypertension." (PMID 24739042, 2014). "IL-6 overexpression in mice induces pulmonary vascular remodeling that is similar to that seen in patients with pulmonary hypertension and induces pulmonary hypertension via proliferative and antiapoptotic mechanisms." (PMID 24804145, 2014). "Similar findings were obtained in mice by injections of supraphysiological doses of IL-6 that resulted in pulmonary hypertension, an effect that was even pronounced under hypoxic conditions." (PMID 24739042, 2014). "This review summarizes the latest clinical and experimental developments in inflammation associated with pulmonary hypertension with special focus on Interleukin-6, and its role in vascular remodeling in pulmonary hypertension." (PMID 24739042, 2014). "Of the various cytokines that are generated downstream of the phosphorylation and activation of the p38 pathway, IL-6 was recently highlighted because of its important role in pulmonary vascular remodeling and pulmonary hypertension." (PMID 23152932, 2012). "Among inflammatory cytokines, interleukin-6 (IL-6) has recently been shown to play a prominent role in the development of pulmonary hypertension." (PMID 22194859, 2011). "IL-1 also increased directly IL-6 mRNA levels by a protein kinase C-independent mechanism and IL-1 receptor antagonist treatment reduces pulmonary hypertension generated in rats by monocrotaline." (PMID 21906276, 2011). "Recent accumulating evidence indicates a pathologic role for IL-6 in promoting proliferation of both smooth muscle and endothelial cells in the pulmonary arterioles, resulting in development of pulmonary arterial hypertension (PAH)." (PMID 20981316, 2010).
pulmonary hypertension (continued). "Patients with pulmonary hypertension were more likely to have higher IL-6 (odds ratio = 1.31, 95% confidence interval = 1.04 to 1.67) and IL-13 (odds ratio = 1.42, 95% confidence interval = 1.04 to 1.94)." (PMID 19799786, 2009). "Lastly, patients with interstitial lung disease had elevated IL-6 and patients with pulmonary hypertension had elevated IL-6 and IL-13." (PMID 19799786, 2009). "IL‐6 signals via STAT3 and knowing that STAT3 signaling is linked to both pulmonary hypertension and inflammation, we studied whether total STAT3 and Tyr705 phosphorylation were increased in the investigated organs during hypoxia." (PMID 39034131, 2024). "In animal models of pulmonary hypertension, overexpression of the A2BAR has been associated with increased levels of remodelling agents (e.g., IL-6 and matrix metalloproteinases) and signalling molecules implicated in the pathogenesis of PAH, such as endothelin-1." (PMID 37402944, 2024). "Finally, HIMF can also induce hypoxia inducible factor-1 (HIF-1), VEGF-A, and IL-6, which can stimulate hypoxic inflammation and pulmonary hypertension." (PMID 33800244, 2021). "Exposure to extracellular heme in SCD can also augment the expression of placental growth factor (PlGF) and interleukin-6 (IL-6), with important consequences to enthothelin-1 (ET-1) secretion and pulmonary hypertension, and potentially the development of renal and cardiac dysfunction." (PMID 33584641, 2020). "IL-6 induction may become uncontrolled, contributing to the development of pulmonary hypertension 233,234." (PMID 31024947, 2019). "Moreover, both IL-6-overexpressing mice and TNF-α-overexpressing mice induced spontaneously pulmonary hypertension and pulmonary vascular remodeling, while IL-6 knockout inhibited the development of pulmonary hypertension induced by chronic hypoxia." (PMID 31815093, 2019). "For instance, senescence of pulmonary artery smooth muscle cells may induce pulmonary hypertension by enhancing proliferation and migration of surrounding smooth muscle cells due to IL‐6 and IL‐8 secretion." (PMID 29045001, 2018). "Furthermore, IL-6 has been shown to impact the development of pulmonary hypertension in COPD patients." (PMID 28469671, 2017). "IL-6 is significantly increased in the serum of pulmonary hypertension patients." (PMID 26079807, 2015). "A further association was found between the presence of pulmonary hypertension in COPD patients and polymorphisms of the IL-6 gene: patients with the GG phenotype (-174G/C) of the IL-6 gene had higher pulmonary pressure than patients with the CC or GC phenotype." (PMID 24739042, 2014). "Bcr and Abr play a critical role in down-regulating hypoxia-induced pulmonary hypertension by deactivating Rac1 and, through this, reducing both oxidative stress generated by leukocytes as well as p38 phosphorylation, IL-6 production and proliferation of pulmonary arterial smooth muscle cells." (PMID 23152932, 2012). "For example, IL-6 treated mice are prone to develop hypoxia-induced pulmonary hypertension which may be mediated in part by an inflammatory process." (PMID 23316102, 2012). "IL-6 has recently been shown to play a prominent role in the development of pulmonary hypertension." (PMID 22194859, 2011). "This hypothesis is confirmed experimentally as interleukin-6 overexpression induces pulmonary hypertension in mice." (PMID 21906276, 2011). "Moreover, IL-6 levels are elevated in patients with COPD, where it is thought to influence inflammatory responses that contribute to pulmonary hypertension associated with this disorder." (PMID 21799929, 2011). "Our data suggest that complement activation may play a role in stimulating IL-6 production in pulmonary hypertension since IL-6 expression was increased in hypoxic WT mice but not in C3 −/− mice." (PMID 22194859, 2011).